BTK (Bruton tyrosine kinase)
Diseases named in the same sentence as BTK in open-access papers (continued):
Sharing a sentence is not in itself a finding about the gene and the disease.
cancer (continued). "Up to June 2020, 24 BTK inhibitors are still developing in the cancer field, and half of them are in the clinical development phase." (PMID 33122850, 2021). "Bruton's tyrosine kinase (BTK), a cytoplasmic tyrosine kinase, is the only member of the Tec family of kinases that has been related to the pathogenesis of cancer in humans." (PMID 34457331, 2021). "For additional recent reviews on BTK inhibitors see for the chemical point of view and the development of BTK inhibitors in cancers, respectively." (PMID 34349760, 2021). "These should be complemented by ex vivo studies of NLRP3 activity in cancer patients treated with the increasingly specific BTK inhibitors or biomaterial from healthy volunteers and XLA patients." (PMID 33718366, 2021). "Gene silencing of BTK or inhibition of BTK with ibrutinib or acalabrutinib attenuates the proliferation, migration, invasion and stemness of these cancer cells both in vitro and in vivo." (PMID 34778053, 2021). "Ibrutinib (Imbruvica, PCI-32765), a small-drug inhibitor of BTK, has been examined in several preclinical and clinical cancer studies." (PMID 33640903, 2021). "In the current study, we investigated the in vitro chemosensitizing effect of a BTK inhibitor branebrutinib in P-gp-overexpressing multidrug-resistant cancer cells." (PMID 34350184, 2021). "Poseltinib had a comparably robust inhibitory effect on BTK as ibrutinib which approved as BTK inhibitor for anti-cancer therapy." (PMID 34548595, 2021). "In some cases, focusing on BTK inhibition has proven to be a viable therapy for cancer patients while others have shown BTK inhibitors have dismal effects on patient outcome." (PMID 34063667, 2021). "The maturation of data from these trials will provide valuable insights regarding the clinical impact potential of BTK inhibition as part of multimodality treatment regimens for difficult-to-treat forms of cancer." (PMID 33937249, 2021). "The increased interest in BTK inhibition in cancer has resulted in many preclinical studies that are testing the efficacy of using single-agent BTK inhibitors." (PMID 33818636, 2021). "We additionally found that WA silences BTK expression in GC-resistant MM cells at the mRNA and protein level, suggesting that WA suppresses BTK cancer signaling via a dual mechanism." (PMID 33807411, 2021). "Compound 4 showed enhanced anti-proliferative activity against B-lymphoma Ramos and Raji cell lines with good selectivity, as well as efficiently blocking BTK downstream pathways and stimulating cancer cell apoptosis." (PMID 34885993, 2021). "Taken together, these findings indicate that silencing BTK at least partly promotes cancer immune response by targeting TIM-3 signaling." (PMID 33640903, 2021). "The OSCC database from TCGA revealed that radioresistant or chemoresistant cancer cells highly expressed the BTK gene." (PMID 33640903, 2021). "In detail, exogenous ADO decreases phosphorylation of BTK with a consequent decrease in Ca2+ influx in B cells of healthy donors and cancer patients, and this effect is dependent on the ADO receptor A2." (PMID 32146518, 2020). "Experimentation with recombinant AKR1C3 and different cancer cells expressing this enzyme outlined BTK-inhibitors as potential partners to synergise daunorubicin cytotoxicity in vitro." (PMID 33322571, 2020). "Ibrutinib, an irreversible covalent inhibitor of BTK, is an approved drug to treat CLL and other BTK-driven cancers." (PMID 32718354, 2020). "The goal of blocking BTK signaling with either BTK inhibitors or degraders is to inhibit the growth of cancer cells." (PMID 32848159, 2020). "It is well known that BTK plays a crucial role in oncogenic signalling and is responsible for the proliferation and survival of cancer cells." (PMID 32912025, 2020). "This revealed a synergistic effect of BTK inhibitors on Dau cytotoxicity in cancer cells expressing AKR1C3 both exogenously and endogenously, thus reverting anthracycline resistance in vitro." (PMID 33322571, 2020).
cancer (continued). "This effort led to the discovery of multiple antiviral compounds, including QL47, a cysteine-reactive small molecule that inhibits the proliferation of Bruton's tyrosine kinase (BTK)–dependent cancer cell lines." (PMID 31914414, 2020). "Lately, the Bruton’s tyrosine kinase (BTK) has emerged as one of such pleiotropic genes, with opposing effects in cancer pathways." (PMID 30337526, 2018). "As a result, there is currently a considerable interest in BTK inhibition as an anti-cancer therapy, not only in B cell malignancies but also in solid tumors." (PMID 29455639, 2018). "In this review, we discuss the role of BTK in B cell differentiation and B cell malignancies and highlight the importance of BTK inhibition in cancer therapy." (PMID 29455639, 2018). "In cancer immunotherapies, first results on BTK inhibition modulating DC and subsequent CD4+ T cell activation or upregulation of the inhibitory receptor TIM-3 on DCs are also noteworthy." (PMID 29167667, 2017). "Ibrutinib, a Bruton’s tyrosine kinase (BTK) inhibitor, is a novel anticancer drug used for treating several types of cancers." (PMID 28716053, 2017). "Target: Bruton's tyrosine kinase inhibitorMechanism of action:Inhibits BTK and activates pathways necessary for B-cell trafficking, chemotaxis, and adhesion.Promotes cancer cell apoptosis, inhibits cell proliferation." (PMID 27119356, 2016). "Analysis of the Cancer Cell Line Encyclopedia demonstrated that AML cells expressed levels of BTK mRNA similar to B-cell malignancies." (PMID 26624983, 2016). "Emerging molecular variants such as Bruton tyrosine kinase (BTK) and Ephrin type-A receptor 5 (EPHA5) promote metabolic reprogramming, drug resistance, and metastasis, and cancer stem cells’ (CSCs) persistence contributes to adaptation to therapy and recurrence." (PMID 41373772, 2025). "Although several BTK mutations have been well documented, D326E has not been previously reported in ovarian or any other cancers." (PMID 39925800, 2025). "An emerging and significant application of BTK inhibitors is in the field of cancer therapeutics." (PMID 39063112, 2024). "Full inhibition of tissue-resident mast cells may require different BTK inhibitor dosing than what is used for treating cancers." (PMID 37384412, 2023). "In addition, the off-target kinases of BTK inhibitors provide a possibility to expand the use of these inhibitors in other cancers." (PMID 36913160, 2023). "As BTK inhibitors are given orally, they may be a suitable option for patients who have difficulty travelling to cancer centers for treatment or who may wish to reduce public exposure to prevent infections." (PMID 37185435, 2023). "Although there are limitations to this study, it suggests that patients on BTK inhibitors may benefit from cancer screening, particularly for lung cancer and melanoma to support early detection, leading to better prognosis." (PMID 37185435, 2023). "Nevertheless, the therapeutic effect of silencing BTK by RNA interference in cancers with upregulated BTK highlights the potential that targeting increased expression may be beneficial." (PMID 38022591, 2023). "One tyrosine kinase often found to be dysregulated in cancer is Bruton’s tyrosine kinase (BTK)." (PMID 36612306, 2023). "Intratumor heterogeneity has been shown to be prognostic in certain cancer types and can also explain the partial efficacy of targeted therapies or why it is impossible to achieve complete responses with BTK inhibitors as monotherapy in WM." (PMID 37493341, 2023). "In addition to its dominating space in signal transduction mediated through BCRs, increasing evidence shows the impact of BTK in other subtypes of cancers." (PMID 36986499, 2023).
cancer (continued). "As epigenetic alterations like changes in DNA methylation are common characteristics of cancer cells, we wondered whether BTK-p80/p65 expression could possibly be regulated by methylation in HNSCC." (PMID 36612306, 2023). "As a result, lacking the region responsible for negative regulation, could explain aberrant expression and activation of BTK-p65 in cancer." (PMID 36612306, 2023). "Recent studies have evaluated the anti-cancer activity of BTK inhibitors in solid tumours." (PMID 34894949, 2022). "The inhibition of the cancer cells may be induced by BTK inhibition, which triggers the apoptosis and autophagy pathways." (PMID 34894949, 2022). "However, the focus of this review is on the role of BTK in myeloid cells and the therapeutic implications of targeting BTK in cancer and microbial infections." (PMID 33818636, 2021). "For example, if BTK is largely expressed in non-cancer cell (e.g., immune cell) populations within GBM tissue, its inhibition with BTK targeted drugs might be considered a type of immunotherapy rather than cancer cell therapy." (PMID 34645618, 2021). "Clinical trials using BTK inhibitors are known to target different cancer including GBM (NCT03535350), prostate (NCT02643667), oesophagogastric (NCT02884453), refractory colorectal (NCT03332498), and immune cell populations in COVID-19 disease (NCT04382586, NCT04439006, and NCT04346199)." (PMID 34645618, 2021). "Given that nearly half of the agents used in cancer therapy today are either natural products or derivatives thereof, novel BTK-targeting lead compounds may be identified from this vast arsenal of chemically active structures." (PMID 33807411, 2021). "Also, BTK inhibition impaired IL-1β processing and release in human primary macrophages from healthy donors, ibrutinib-treated cancer patients, and patients with Muckle–Wells syndrome—an autoinflammatory disease characterized by excessive production of IL-1β." (PMID 33818636, 2021). "However, our data highlight the pronounced heterogeneity of BTK protein expression in distinct cell types including cancer stem-like cells (SOX2), TAMs (CD163) and microglia (CD68)." (PMID 34645618, 2021). "Since p21 localization and expression levels have been shown to impact drug resistance in cancer cells, BTK activity could potentially work through this mechanism." (PMID 34307353, 2021). "This suggests that the unusual expression of BTK after chemo- or radiotherapy might play a regulatory role in cancer cells." (PMID 33640903, 2021). "We supposed that CCRT-resistant cancer cells, which might be CSCs, expressed BTK and influenced patient survival." (PMID 33640903, 2021). "Low-dose BTZ might further enhance the anti-cancer effect of low-dose BGB-3111 in MCL expressing BTK, suggesting that the combination of low-dose BGB-3111 and low-dose BTZ is a potential and effective therapeutic strategy for MCL patients." (PMID 34508613, 2021). "Over the past decade, numerous preclinical and clinical studies are evaluating the efficacy of BTK inhibitors as single agents or in combination with other standard chemotherapy, immunotherapy, or targeted agents in various cancers to broaden indications and expand markets." (PMID 33122850, 2021). "Importantly, the clinically approved covalent BTK inhibitor ibrutinib has been approved for use in cancer patients." (PMID 34784299, 2021). "The repurposing of FDA-approved Bruton’s tyrosine kinase (BTK) inhibitors as therapeutic agents for solid tumors may offer renewed hope for chemotherapy-resistant cancer patients." (PMID 33937249, 2021). "Such complex cell culture models might better define how BTK inhibitors impact on cancer regression or BTK inhibitor resistance." (PMID 34645618, 2021). "Ibrutinib is used for cancer therapy and suppresses Bruton tyrosine kinase (Btk) below the BCR." (PMID 34445084, 2021).
cancer (continued). "In the recent single‐centre (The Ohio State University Comprehensive Cancer Centre), retrospective cohort study (from 2009 to 2017), Bond and colleagues reported the incidence of second cancer in ∼700 patients with CLL receiving BTK inhibitors (median age of 61, and 21% receiving acalabrutinib)." (PMID 35846092, 2021). "The BTK pathway, although necessary for B cell maturation and, as result, vital for proper immune system function, has shown its pertinence as it relates to cancer progression, making it an ideal candidate for exploitation as a cancer therapy." (PMID 34063667, 2021). "BTK is a dominant bioactive kinase expressed within both cancer and immune cells of GBM tissue." (PMID 34645618, 2021). "Furthermore, pharmacological inhibitors of BTK and p110δ have shown a strong convergence of clinical activity in cancer, with best responses in malignancies of mature B-cells." (PMID 34356110, 2021). "New BTK inhibitors developed by indole derivatives also appeared for related cancer treatments." (PMID 32984343, 2020). "Furthermore 31 demonstrated unique selectivity over the other JAKs and also BTK and in in vitro studies it showed excellent antiproliferative activity in T cell cancer lines." (PMID 33479617, 2020). "Interestingly, we and others have observed associations between several tyrosine kinases (i.e., BTK, Src, Tec) and AKT and ERK signaling in inflammation- and neuroinflammation-associated diseases (i.e., cancer, CML)." (PMID 31655606, 2019). "Therefore, this study not only suggested an effective strategy to improve the anti‐cancer activity of BTK inhibitors against solid tumors, but also provided meaningful insights into the design and development of kinase inhibitory agents." (PMID 30663221, 2019). "BTK inhibitors have emerged as crucial therapeutic agents for distinct cancer treatment." (PMID 28686599, 2017). "The unexpected description of (so far) cancer-specific alternative isoforms, p65 and p80, in breast, brain, prostate, gastric, and colon cancer as well as reports for a role of BTK in NK cells, and platelets also deserve mention and warrant further research." (PMID 29167667, 2017). "BTK may therefore represent a novel potential target for reduction of Breg cell activity in cancer, and furthermore BTK inhibition may augment the efficacy of chemotherapy." (PMID 27437104, 2016). "Lentiviral vectors insert into the genome semi-randomly, increasing the risk of deleterious effects if BTK is expressed at non-physiological levels or in inappropriate cell types, disrupting signaling pathways, and heightening the likelihood of cancer development." (PMID 40917692, 2025). "22.0405.aF demonstrated an additive effect in cell killing in the presence of venetoclax or ibrutinib, thus supporting that the addition of 22.0405.aF to current treatment paradigms may yield stronger clinical responses in patients with cancer treated with BTK inhibitors or venetoclax." (PMID 41479906, 2025). "Notably, BTK signaling was identified as a key pathway, which is well known for its role in B cell maturation, but it is also critical for cancer cell proliferation and evasion of cancer‐killing cells." (PMID 40809351, 2025). "Moreover, high levels of BTK (Bruton tyrosine kinase) in ciBMSCs could promote cancer cell growth and progression." (PMID 40809351, 2025). "Unlike its predecessors that only inhibit wildtype BTK, pirtobrutinib has additional activity on mutant BTK with cysteine-481 substitution mutations, which are the most common acquired mutations that confer cancer resistance to BTKis." (PMID 38492772, 2024). "Cancer, autoimmunity, or inflammation may be a result of dysregulated BTK pathways." (PMID 34277564, 2021). "This strategy can also be used for therapeutic targets that are not mutated in cancer, such as BTK." (PMID 32272741, 2020).
cancer (continued). "With the rapid clinical development of novel agents of bispecific antibodies, antibody-drug conjugates, immune checkpoint blockers, and CAR-T for cancer immunotherapies, combinations of BTK inhibitors with novel agents may overcome acquired resistance in refractory B cell malignancies." (PMID 27776353, 2017). "GBD-9 efficiently degraded BTK and GSPT1 proteins with high efficiency (BTK (90%) and GSPT1 (80%) at 50 nM concentration) and inhibited cancer cell growth by recruiting CRBN in a range of DLBCL and AML cell lines." (PMID 40793752, 2025). "Clinical trials evaluating the combination of BTK or BCL-2 inhibitors with ROR1-targeting therapies have yielded encouraging results, further underscoring the critical role of ROR1 in cancer progression and therapy resistance." (PMID 41479906, 2025). "With diverse targets including androgen receptors, BTK, estrogen receptors, BET proteins, and BRAF, PROTACs offer a versatile strategy for personalized cancer treatment." (PMID 39898116, 2025). "Ibrutinib, developed primarily as a BTK inhibitor, exhibits nanomolar affinity for ERBB4 and has been shown to suppress cell growth and MEK and ERK signaling in cancer cell lines." (PMID 41256885, 2025). "Analysis of mRNA expression in TCGA paired samples revealed notably enhanced levels of LDHA, SHC1 and CDKN3 in cancer tissues compared to adjacent tissues, whereas PCSK9, BTK, CAV2 and PDGFB showed significantly reduced expression." (PMID 40182622, 2025). "First, there is a lack of robust, prospective data evaluating the long-term effectiveness of cancer screening, vaccinations, and IVIG replacement in patients with CLL and also in patients with CLL receiving targeted therapies such as BTK or BCL-2 inhibitors." (PMID 40647394, 2025). "RN486, a Bruton’s tyrosine kinase (BTK) inhibitor, has been shown to antagonize ABCG2-mediated resistance in preclinical models, enhancing drug retention in ABCG2-overexpressing cancer cells." (PMID 40547482, 2025). "The diverse range of targets, including androgen receptors, BTK, estrogen receptors, BET proteins, and BRAF, underscores the versatility of PROTACs in tailoring therapeutic strategies for specific cancer types." (PMID 39898116, 2025). "The synergistic antitumor capacity indicates that double inhibition of BTK and HDAC is a potential new approach for cancer treatment, and the combined drugs are a potential treatment strategy for DLBCL." (PMID 38381215, 2024). "This review article provides a comprehensive insight into the rationale for and approaches to detect BTK inhibition in MCL cells, as the model for cancer therapy with kinase inhibitors." (PMID 39161974, 2024). "The CXC-chemokine receptor-4 (CXCR4) pathway plays a role in cancer cell homing and metastasis, representing a potential target for cancer therapy, i.e., CXCR4 activates mTOR and the Bruton tyrosine kinase." (PMID 39411551, 2024). "BTK and JAK3 are two important enzymes that can be potentially targeted to inhibit downstream signaling pathways related to cancer cell growth." (PMID 37894618, 2023). "Altogether, while additional studies are needed to clarify the impact of treating cancer with a combination of PD-1 blockade and ITK/BTK inhibitors, this possibility is mechanistically promising and clinically feasible with current approved drugs." (PMID 35911672, 2022). "Cenisertib inhibits the kinase activity of AKT as well as FLT3, VEGFR2, LYN, BTK, and KIT and promotes growth inhibition, cell cycle arrest, and apoptosis in many cancer cell lines." (PMID 36590916, 2022). "For example, PROTACs targeting AR, BR, BTK, Tau, IRAK4, and other proteins have shown unprecedented clinical efficacy in cancers, neurodegenerative diseases, inflammations, and other fields." (PMID 36142231, 2022). "BTK, a member of the TEC family of kinases, has recently been identified as a promising target for cancer therapy because of its critical role in B-cell activity and malignancy." (PMID 36276869, 2022).